GLIS3 (GLIS family zinc finger 3)
Diseases named in the same sentence as GLIS3 in open-access papers (continued):
Sharing a sentence is not in itself a finding about the gene and the disease.
diabetes (continued). "A significantly increased HbA1c was found among patients with type 2 diabetes and with GADA-positive diabetes carrying rare GLIS3 variants compared to non-carriers of rare GLIS3 variants with diabetes (p = 0.02 and p = 0.004, respectively)." (PMID 31415576, 2019). "The Glis3-null mice die within 1 week after birth due to the severity of neonatal diabetes." (PMID 30555422, 2018). "We show that decreased expression of GLIS3 may contribute to diabetes by favouring beta cell apoptosis." (PMID 23737756, 2013). "However, after HFD feeding for 20 weeks, Glis3+/− mice developed diabetes with significantly higher fasting blood glucose." (PMID 23197416, 2013). "Therefore, to exclude neonatal diabetes and hyperglycemia as variables, we analyzed mitochondrial and metabolic gene expression and functions in kidney-selective GLIS3-deficient (Glis3-Pax8Cre) mice that do not develop neonatal diabetes." (PMID 39505148, 2024). "Similarly, genes ABCB11 (chromosome 2), ADCY5 (chromosome 3), CDKAL1 (chromosome 6), ANK1 (chromosome 8), GLIS3 (chromosome 9), and HKDC1 (chromosome 10) have been linked to various aspects of diabetes, including insulin release, glucose levels, β-cell function, and insulin resistance." (PMID 38274506, 2023). "Moreover, a high-content chemical screening based on GLIS3−/− hESCs derivatives identified a drug candidate, galunisertib, that could be used for treatment of GLIS3-associated diabetes." (PMID 33751396, 2022). "As an example, the gene GLIS3, which has been implicated in diabetes and does not seem to have a major role in the brain, is actually located next to SLC1A1 (encoding the high-affinity glutamate transporter) which has been associated with obsessive-compulsive disorder and psychosis." (PMID 34326310, 2021). "In addition to NKX6–1 we found variants in WFS1, RFX6 and 7 other genes associated with monogenic forms of diabetes (AKT2, EIF2AK3, GLIS3, HADH, MNX1, NKX2–2, and PTF1A) and they may be relevant to development of MODY." (PMID 29439679, 2018). "Unlike human patients with GLIS3 mutations, the medaka pc mutant shows none of the symptoms of a pancreatic phenotype, such as impaired insulin expression and/or diabetes, suggesting that the pc mutant may be suitable for use as a kidney-specific model for human GLIS3 patients." (PMID 19609364, 2009). "The mRNA expressions of GCK, GCKR, GLIS3 and CDKN2B, known to be related to diabetes mellitus, were examined by RT-PCR." (PMID 37049638, 2023). "Candidate target genes also included six genes involved in MODY and other monogenic and syndromic forms of diabetes (ABCC8, KCNJ11, GCK, INS, GLIS3, WFS1)." (PMID 31064983, 2019). "The coding regions of GLIS3 were sequenced in 53 MODYX patients, 2,930 patients with T2D, 5,724 non-diabetic individuals and 206 patients with GADA-positive diabetes." (PMID 31415576, 2019). "Notably, further adjustment for family history of diabetes, lipid profile, medication information and hypertension did not materially change the associations of GLIS3-rs7034200 with HOMA-B and type 2 diabetes, but abolished the association between CRY2 and combined IFG/type 2 diabetes." (PMID 21747906, 2011). "The spectrum of causative genes (PTF1A, GLIS3, WFS1, INSR, SLC29A3, ZNF808, ABCC8, INS) is markedly different from the monogenic diabetes genes seen in non-consanguineous cohorts, and also different from those seen in other consanguineous populations." (PMID 37897565, 2023). "In addition, isolated compounds 3, 4, 6 and 7 had an effect that significantly changed the mRNA expressions of GCK, GCKR, GLIS3 and CDKN2B, which are related to diabetes mellitus in the alloxan-induced zebrafish." (PMID 37049638, 2023). "Prolactin can protect β-cells from ER stress through the JAK2/STAT5 pathway, transcription factors such as GLIS3 can enhance INS gene expression, rapamycin can improve diabetes and further down-regulate β-cell apoptosis, and induced pluripotent stem cells can promote β-cell regeneration." (PMID 36686471, 2022).
diabetes (continued). "Quantitative analysis of rare GLIS3 variants in 5,726 non-diabetic individuals, 2,930 patients with T2D and 206 patients with GADA-positive diabetes." (PMID 31415576, 2019). "Some case studies indicate that patients with a GLIS3 gene mutation resulting in a truncated non-functional protein demonstrated IUGR.In addition, patients with disturbances in the GLIS3 gene demonstrate impaired beta cell function and an altered fasting glucose and diabetes mellitus phenotype." (PMID 31041507, 2019).
congenital hypothyroidism (31 papers, 2009 to 2026). A thyroid hormone deficiency present from birth. "GLIS3 mutations exemplify this category, causing a syndrome defined by Neonatal Diabetes, Congenital Hypothyroidism, and Congenital Glaucoma (NDH)." (PMID 41614934, 2026). "For instance, mutations in GLIS3 are not only responsible for NDM but also manifest as a syndromic presentation involving congenital hypothyroidism, congenital glaucoma, and renal cysts, reflecting the gene’s pleiotropic role in multiple endocrine organs." (PMID 41614934, 2026). "The sibling pair had a large homozygous deletion in the GLIS3 gene causing neonatal diabetes and congenital hypothyroidism." (PMID 37897565, 2023). "Loss of the transcription factor GLI-Similar 3 (GLIS3) function causes congenital hypothyroidism (CH) in both humans and mice due to decreased expression of several thyroid hormone (TH) biosynthetic genes in thyroid follicular cells." (PMID 36793061, 2023). "We report a preterm female neonate with coarse facial features and hyperglycemia, later diagnosed with neonatal diabetes mellitus, congenital hypothyroidism (CH), congenital glaucoma (CG), and renal cysts, secondary to GLIS3 gene mutation." (PMID 36312692, 2022). "The relation with both TSH and FT4 for GLIS3 has been described in literature, which is based on rare mutations leading to congenital hypothyroidism." (PMID 35262175, 2022). "Lastly, patients with congenital hypothyroidism (due to GLIS3 mutations, for example) can acquire resistance to the action of thyroid hormones." (PMID 34671932, 2022). "In agreement with these phenotypes, human biallelic mutations in GLIS3 underlie a rare clinical syndrome, characterized by neonatal diabetes and congenital hypothyroidism." (PMID 34295307, 2021). "Biallelic mutations of GLIS3 underlie a rare clinical syndrome, characterized by neonatal diabetes and congenital hypothyroidism." (PMID 34295307, 2021). "Neonatal diabetes with congenital hypothyroidism (NDH) syndrome is a rare disorder caused by autosomal recessive mutations in the GLI-similar 3 (GLIS3) gene." (PMID 33935973, 2021). "One such novel homozygous mutation created a premature stop codon within the C-terminus of GLIS3 (c.2392C>T; p.Gln798Ter) and caused a syndrome characterized by neonatal diabetes, congenital hypothyroidism, congenital glaucoma, and cystic kidney disease." (PMID 34943978, 2021). "Later on, 12 patients with mutations within the GLIS3 gene have presented with a wider phenotype consisting mainly of neonatal diabetes and congenital hypothyroidism, in addition to multiple features involving different organs." (PMID 28253873, 2017). "Mutations in GLIS3 underlie a complex syndrome of congenital hypothyroidism, neonatal diabetes mellitus, and variable other abnormalities including congenital glaucoma, developmental delay, hepatic fibrosis, and polycystic kidneys." (PMID 29026407, 2017). "In summary, patients presenting with mutations in GLIS3 characteristically present with neonatal diabetes with variable insulin sensitivity and congenital hypothyroidism due to a range of underlying causes." (PMID 26259131, 2015). "Mutations in GLIS3 can cause a recessive form of neonatal diabetes and congenital hypothyroidism (OMIM#610199)." (PMID 22662265, 2012). "Human GLIS3 was recently identified as the gene responsible for a neonatal diabetes syndrome associated with congenital hypothyroidism, congenital glaucoma, hepatic fibrosis and polycystic kidneys." (PMID 19609364, 2009). "Biallelic loss-of-function mutations in human GLIS3 leads to a multi-organ phenotype that includes congenital hypothyroidism, while monoallelic, as well as biallelic, single nucleotide polymorphisms in GLIS3 are associated with an increased risk of thyroid dysfunction and CH." (PMID 38281222, 2024).
congenital hypothyroidism (continued). "The GLIS3 gene located in 9p24.2 encodes a nuclear protein that is involved in the expression and development of pancreatic beta cells, and has been associated with neonatal diabetes, fasting blood glucose, type 2 diabetes, and congenital hypothyroidism." (PMID 36979105, 2023). "Loss-of-function mutations within GLIS3 lead to a rare syndrome mainly characterized by neonatal diabetes and congenital hypothyroidism in humans, and in accordance with this, GLIS3(−/−) mice develop neonatal diabetes caused by impaired pancreatic beta-cell generation and insulin production." (PMID 32226409, 2020). "We report a new case for consanguineous parents with homozygous novel mutation in GLIS3 gene who presented with neonatal diabetes mellitus, severe resistant congenital hypothyroidism, cholestatic liver disease, bilateral congenital glaucoma and facial dysmorphism." (PMID 28253873, 2017). "GLIS3 is highly expressed in the thyroid, and congenital hypothyroidism in patients with GLIS3 mutations may be associated with either thyroid dysgenesis or a eutopic but histologically abnormal thyroid gland." (PMID 29026407, 2017). "NDM patients with GLIS3 gene mutation may also manifest congenital hypothyroidism, glaucoma, liver fibrosis, and polycystic kidney disease." (PMID 26839896, 2016). "We hypothesize that reduced expression of a set of genes rather than one particular single gene is causing the TM abnormalities and high IOP in GLIS1 deficiency, as we reported for the development of congenital hypothyroidism and neonatal diabetes in Glis3-KO mice." (PMID 34385434, 2021). "Mutations in the GLI-similar 3 (GLIS3) gene encoding the transcription factor GLIS3 are a rare cause of neonatal diabetes and congenital hypothyroidism with 12 reported patients to date." (PMID 28253873, 2017). "Mutations in GLIS3 (Gli-similar 3) result in the concomitant presentation of PND and congenital hypothyroidism." (PMID 26259131, 2015). "Loss of GLI-Similar 3 (GLIS3) function in mice and humans causes congenital hypothyroidism (CH)." (PMID 37461635, 2023). "We report the first case of a patient with a compound heterozygous mutation in GLIS3 who did not present with congenital hypothyroidism." (PMID 26259131, 2015). "Patient 1 is the first patient described with biallelic GLIS3 mutations, who does not have congenital hypothyroidism, and she has a milder phenotype than other patients in the cohort." (PMID 26259131, 2015). "This difference could be related to its underlying biology related to early life rather than aging as GLIS3 is associated with thyroid development and mutations in this gene are associated with neonatal diabetes and congenital hypothyroidism." (PMID 37530217, 2023). "Among them, the reported signals at SOX9, ABO, SASH1, GLIS3 and MIR1179 will need to be confirmed in other studies; but one of them - GLIS3- is a prime candidate, because it is involved in congenital hypothyroidism." (PMID 23408906, 2013).
type 2 diabetes (27 papers, 2010 to 2025). "On the basis of functional genetics, we identified 18 P/LP heterozygous GLIS3 variants that increase type 2 diabetes risk." (PMID 38051360, 2024). "We then assessed the effect of the burden of the 18 rare P/LP GLIS3 variants on type 2 diabetes risk." (PMID 38051360, 2024). "The meta-analysis of association studies obtained from RaDiO, 52K and TOPMed showed an enrichment of P/LP GLIS3 variants in individuals with type 2 diabetes (p=5.6×10−5; OR 2.1 [95% CI 1.4, 2.9])." (PMID 38051360, 2024). "Rare pathogenic, bi-allelic mutations in GLIS3 cause syndromic neonatal diabetes whereas frequent SNPs at this locus associate with common type 2 diabetes risk." (PMID 38051360, 2024). "GLIS3 mutations have been detected in relation to neonatal, type 1, and type 2 diabetes, reflecting its function in pancreatic β-cells, where it is a drug candidate for treating a broad range of GLIS3-associated diabetic patients." (PMID 35743950, 2022). "Single Nucleotide Polymorphisms (SNPs) within GLIS3 have been linked to both Type 1 and Type 2 diabetes, as well as gestational diabetes and decreased β-cell function." (PMID 34943978, 2021). "Genetic deletion of GLIS3 in mice and humans induces neonatal diabetes, while single nucleotide polymorphisms (SNPs) in GLIS3 have been associated with both Type 1 and Type 2 diabetes." (PMID 34943978, 2021). "And GLIS3 is one of only a few genes that have been linked through GWAS to both Type 1 and Type 2 diabetes." (PMID 34943978, 2021). "For example, by examining other large type 2 diabetes GWAS analyses and a larger type 1 diabetes genetic analysis, we conclude that the association near GLIS3 likely does co-localise between the two diseases, and with concordant directions of effect." (PMID 33830302, 2021). "Examination of additional trans-ethnic and East Asian type 2 diabetes genetic analyses indicated that a fifth association, near GLIS3, is likely to co-localise between diseases, with concordant direction of effect." (PMID 33830302, 2021). "Rare missense variants in GLIS3 associates nominally with increased level of HbA1c and increased risk of developing type 2 diabetes." (PMID 31415576, 2019). "Earlier, GLIS3 gene polymorphisms have been shown to be associated with the development of maturity onset diabetes of the young (MODY)." (PMID 29606121, 2018). "Among them, MAEA and GLIS3 loci were significantly associated with type 2 diabetes after correction for multiple testing." (PMID 27053236, 2016). "The critical role for Glis3 in maintaining ß cell function is supported by GWAS studies implicating GLIS3 as a risk locus for type 1 and type 2 diabetes." (PMID 26147758, 2015). "Taken together, our studies provide a molecular basis for the GLIS3 locus conferring susceptibility to type 1 and type 2 diabetes, both of which involve defects in beta cell function (in the presence of insulin resistance in the case of the type 2 disease)." (PMID 23197416, 2013). "Recent genome-wide association studies (GWAS) in adult populations identified GLIS3 as a candidate gene for type 1 diabetes, and as a gene that is associated with type 2 diabetes." (PMID 23197416, 2013). "The GLIS3 gene region has also been identified as a susceptibility risk locus for both type 1 and type 2 diabetes." (PMID 23737756, 2013). "Genome-wide association studies identified GLIS3 as a susceptibility locus for type 1 and type 2 diabetes." (PMID 23197416, 2013). "In conclusion, our results indicate the associations of GLIS3 locus with type 2 diabetes and impaired fasting glucose in Chinese Hans, partially mediated through impaired beta-cell function." (PMID 21747906, 2011). "Consistent with their observation, we found that impaired beta-cell function estimated by HOMA-B explained about 63% of the association between GLIS3-rs7034200 and type 2 diabetes, and further adjustment for HOMA-B abolished this association." (PMID 21747906, 2011).
type 2 diabetes (continued). "HOMA-B explained 63% of the association between GLIS3-rs7034200 and type 2 diabetes, calculated by comparing the expected effect with the observed effect." (PMID 21747906, 2011). "Further analyses suggested that association between GLIS3-rs7034200 and type 2 diabetes was mediated by HOMA-B." (PMID 21747906, 2011). "Consistent with our results, a recent study in case-control samples of Chinese Hans also observed a significant association between GLIS3-rs7034200 and type 2 diabetes." (PMID 21747906, 2011). "The GLIS3 rs7034200 SNP only displayed a weak association with type 2 diabetes in the MAGIC study, although there is evidence that this variant confers risk of the disease in a Chinese population." (PMID 21949744, 2011). "Results of Mendelian randomization analyses for the associations of GLIS3-rs7034200 with type 2 diabetes, IFG and combined IFG/type 2 diabetes." (PMID 21747906, 2011). "Additionally, SNPs in presumed regulatory regions within the first and second intron of GLIS3 have been associated with an increased risk of both Type 1 and Type 2 diabetes." (PMID 41369402, 2025). "We wondered whether rare, deleterious GLIS3 variants could be associated with increased risk for common type 2 diabetes, and whether they might impact drug treatment choices." (PMID 38051360, 2024). "Rare P/LP GLIS3 variants do contribute to type 2 diabetes risk." (PMID 38051360, 2024). "In addition, genome-wide association studies (GWAS) identified frequent SNPs at the GLIS3 locus associated with common type 2 diabetes risk, and with variation in fasting glucose and beta cell function." (PMID 38051360, 2024). "Interestingly, all participants with type 2 diabetes carrying a P/LP GLIS3 variant were treated with sulfonylureas, a class of medication that stimulates the secretion of insulin by activating ATP-dependent potassium channels." (PMID 38051360, 2024). "However, through a meta-analysis of RaDiO, TOPMed and 52K studies, we found an enrichment of P/LP GLIS3 variants among individuals with type 2 diabetes (p=5.6×10−5 with an OR of 2.1 [1.4, 2.9])." (PMID 38051360, 2024). "Because rare, functional variants located in other susceptibility genes for type 2 diabetes have already been shown to strongly increase individual risk for common type 2 diabetes, we aimed to investigate the contribution of rare pathogenic GLIS3 variants to type 2 diabetes." (PMID 38051360, 2024). "Interestingly, GLIS3 is one of only a small number of genes that have been linked to both Type 1 and Type 2 diabetes." (PMID 34943978, 2021). "Moreover, a number of genome-wide-association studies (GWAS) have implicated GLIS3 as a risk locus for the development of type 1 and type 2 diabetes." (PMID 26147758, 2015). "Several type 2 diabetes mellitus (T2DM) susceptibility loci have been identified in or near GLIS3, PEPD, FITM2-R3HDML-HNF4A, KCNK16, MAEA, GCC1-PAX4, PSMD6, and ZFAND." (PMID 34822452, 2021). "In addition, we provide evidence that alleles of SNPs in ADCY5 and GLIS3 may confer risk of type 2 diabetes, the first time that this has been reported in South Asian populations." (PMID 21949744, 2011). "The circRNA32 (1334 bp in length) was named circGLIS3, because it is derived from the second and third exons of the maternal gene GLIS family zinc finger 3 (GLIS3), located on chromosome 8, a candidate gene for type 2 diabetes." (PMID 40735833, 2025). "We then analysed the association between P/LP variants in GLIS3 (NM_001042413 [ENST00000381971] transcript) and type 2 diabetes risk in the Type 2 Diabetes Knowledge Portal (using the genetic association interactive tool)." (PMID 38051360, 2024). "Previous work has shown that loci within the GLIS3 gene region have a shared effect on both T1D and type 2 diabetes risks via effects on pancreatic β-cell function, insulin sensitivity and inflammation." (PMID 39263363, 2024).